EGLN1 (egl-9 family hypoxia inducible factor 1)
Diseases named in the same sentence as EGLN1 in open-access papers (continued):
Sharing a sentence is not in itself a finding about the gene and the disease.
cancer (79 papers, 2009 to 2026). A tumor composed of atypical neoplastic, often pleomorphic cells that invade other tissues. "Silencing of EGLN1 could activate the downstream pathway of hypoxia-inducible factor 1α (HIF1α) and Wnt/β-catenin, thus increasing the expression of cancer stem cell (CSCs) associated genes 9,10." (PMID 35517429, 2022). "In fact, EGLN1 haplodeficient cancer cells secrete less TGF-β, which in turn leads to reduced CAF activation." (PMID 41413686, 2025). "EGLN1, which encodes the oxygen sensor PHD2, plays a crucial role not only in the survival of cancer cells but also in regulating other cell types that reside in the TME." (PMID 41413686, 2025). "To investigate the role of EGLN1 in cancer cell self-renewal and differentiation, we detected the effect of EGLN1 on the CSC properties of NPC cells." (PMID 35517429, 2022). "Of these common target genes of miR-495-3p and miR-543, NRAS, HMGA2, and EGLN1 present in KEGG cancer metabolic pathways stand out (p-value < 0.05)." (PMID 35645340, 2022). "Fifty-six genes were identified as significant genes and included cancer-associated genes such as BOK, FANCD2, ADRM1 and EGLN1." (PMID 32437477, 2020). "Among the 10 top-ranked compounds for ELGN3, including Fe as a ligand, eight compounds targeted cancer genes and two out of the eight targeted EGLN1, which is paralog of EGLN3." (PMID 24565165, 2014). "EGLN1 could promote cell proliferation, invasion and migration, and even enhance the cancer stem cells (CSCs) prosperity and radioresistance of NPC cells." (PMID 35517429, 2022). "Moreover, compared with normal epithelial cells, cancer tissues exhibited a relatively high level of expression of EGLN1 (2.100 ± 0.3145 vs 5.363 ± 0.3365, P = 0.007)." (PMID 35517429, 2022). "So far, the activity of EGLN1/PHD2 has been characterized in different cell types, albeit with controversial outcomes in different cancer settings." (PMID 41413686, 2025). "Cytoplasmic P4Hs that hydroxylate HIF-1α, a master transcriptional regulator of cellular responses to hypoxia and well-established mediator of cancer progression, have also been identified (prolyl hydroxylase domain enzymes; PHD1/EGLN2, PHD2/EGLN1, and PHD3/EGLN3)." (PMID 35804902, 2022). "In this study, EGLN1 (Egl-9 family hypoxia inducible factor 1; also known as PHD2) is a risky gene (HR = 1.79, 95% CI: 1.45–2.21) and it is closely related with angiogenesis by regulating the stability of HIF1 in non-CESC cancers." (PMID 30662454, 2018).
infection (13 papers, 2012 to 2026). The state of being infected such as from the introduction of a foreign agent such as serum, vaccine, antigenic substance or organism. "Here the authors explore the role of oxygen in the antiviral innate response in multiple models of infection and suggest oxygen enhances the antiviral innate response via EGLN1 hydroxylation of IRF3." (PMID 38670937, 2024). "Upon infection with Sendai virus (SeV), ectopic overexpression of EGLN1 significantly induced the expression of IFN-β, CXCL10, and CCL5 in HEK293T cells." (PMID 38670937, 2024).
EGLN1 also shares sentences with these, for which no sentence is quoted: breast carcinoma (29 papers); anemia (14); colon carcinoma (11); colitis (10); Obesity (10); chronic kidney disease (8); hepatocellular carcinoma (8); Hypertension (7); head and neck squamous cell carcinoma (6); ischemia (6); gastric cancer (5); non-small cell lung carcinoma (5); osteosarcoma (5); pulmonary fibrosis (5); Stroke (5); cardiomyopathy (4); clear cell renal cell carcinoma (4); Hyperglycemia (4); prostate carcinoma (4); renal cell carcinoma (4); acute myocardial infarction (3); cardiac hypertrophy (3); dilated cardiomyopathy (3); Insulin resistance (3); limb ischemia (3); lung diseases (3); neuroblastoma (3); renal fibrosis (3); Right ventricular hypertrophy (3); skeletal dysplasia (3).
A further 96 diseases each share a sentence with EGLN1 in 2 papers or fewer.